CCR6 (C-C motif chemokine receptor 6)
Diseases named in the same sentence as CCR6 in open-access papers (continued):
Sharing a sentence is not in itself a finding about the gene and the disease.
infection (continued). "We found that in HIV-infected untreated subjects with moderate immune-suppression, CD4+ cells expressing CCR6 and CD161 were depleted, possibly reflecting their permissiveness to infection and redistribution from the blood to the GI tract in progressive infection." (PMID 30763359, 2019). "In contrast, hBD2 may prevent the spread of infection, as it directly inhibits HIV and induces APOBEC3G, but is weakly chemotactic for CCR6+ cells compared with MIP-3α." (PMID 28509877, 2017). "Chemokine receptor analysis revealed reduced expression of CXCR3, CCR7, and CCR6 on NK cells at early time points (days 2 and 4 after virus inoculation), followed by an increased expression of CXCR3 and CCR5 at later time points (days 7-8) of infection." (PMID 24147080, 2013). "The expression of the gut-homing molecules integrin β7, CCR6, and CXCR3 was identified as a “signature” for HIV-specific but not CMV-specific CD4+ T-cells thus providing a new explanation for their enhanced permissiveness to infection in vivo." (PMID 22470433, 2012). "In addition to exhibiting a diminished activation state, total CD8+ T cells from pregnant individuals that experienced breakthrough infection also expressed lower levels of tissue-homing receptors (CXCR4, CCR5, CCR6, and CD29); this effect was again primarily attributable to CD8+ Tcm cells." (PMID 40693463, 2025). "In contrast, IgD+IgMlow classical MBCs and two populations of atypical MBCs (IgM+IgD+ and class‐switched T‐bet+ cells) expressing low or no CXCR5 and CCR6, along with CD127+CD25low TH2‐like memory CD4+ T cells, were associated with reduced odds of symptomatic infection." (PMID 35475529, 2022). "Evaluation of infection-induced changes in CD4 T-cell differentiation at Day 7 revealed a strong phenotypic shift to Th1 effectors (CXCR3+), Th1 polarized Tfh cells (CXCR3+ CXCR5+) and Th1 Th17 (CXCR3+ CCR6+) CD4 T cells as demonstrated by tSNE plots constructed using flow data." (PMID 33483492, 2021). "This is not surprising since most Th17 are α4β7+ and may be due to the effect of the Rh-α4β7 on CCR6+ T cells that we noted in absence of infection." (PMID 31083697, 2019). "This fact suggests that preferential infection of T cells takes place without CCR6 mediation." (PMID 30004409, 2018). "Thus, it can be speculated that antimicrobial peptides LL-37, hBD-3, and HNP-1, in concert modulate neutrophil apoptosis in vivo in the local milieu at the sites of inflammation or infection by utilizing different receptors (e.g., FPRL1, P2X7, CCR6, and P2Y6)." (PMID 23724322, 2012). "However, mice lacking CCR6 showed an increased frequency of IFNγ-producing CD8 cells already on d 3 of infection, indicating a lower activation threshold or the absence of regulatory mechanisms in B6.CCR6−/− mice." (PMID 23028548, 2012). "In contrast, HIV-specific CD8+ T-cells express low levels of CCR6 and CCR4 and thus may be impaired in their ability to colocalize and control viral replication in CCR6+CCR4+ CD4+ T-cells, such as Th17 cells which are highly permissive to infection." (PMID 22470433, 2012). "This analysis prompted us to envision the presence of CD44hi CCR6+ IL17-committed γδ T cells in C2, and NK1.1+ IFNγ/IL-4-committed γδ T cells in C7, both unaffected by infection, suggesting their absence of response to CMV." (PMID 38976755, 2024). "In contrast, CCR6, a marker of Th17 cells, was downregulated by HIV during in vitro but not in vivo infection." (PMID 33910003, 2021). "Yet, the importance of the CCR6/CCL20 axis is by no way diminished in HIV pathogenesis because this receptor- ligand pair is deemed to be actively recruiting TH17 cells and DCs to infection sites, thus helping the virus to propagate to other locations of the body." (PMID 30004409, 2018).
infection (continued). "CXCR3–CCR6+ CD4+ T cells (CCR6+) formed the largest proportion of AIM+CD4+ T cells in both children and adults; however, AIM+CCR6+ cells were reduced in children compared with adults during the acute phase of infection (spike-specific: P = 0.001; non-spike-specific: P < 0.0001)." (PMID 40906527, 2025). "We observed that regardless of the infection state in SFB colonized eSPF mice, within small intestinal LPLs nearly 100% of IL-17A+IL-22- cells expressed CD44+ and lacked CD62L expression with around 70% of them expressing CCR6, which is in contrast to IL-17A-IL-22- cells." (PMID 34566952, 2021).
infectious disease (8 papers, 2020 to 2026). A disorder directly resulting from the presence and activity of a microbial, viral, or parasitic agent in humans. "On the other hand, the role of the MIP3α-CCR6 axis was reported to attract dendritic cells (DC), effector/memory T cells and B cells, thereby taking part in the pathogenesis of inflammatory and infectious diseases and several malignancies." (PMID 36869895, 2023).
inflammation (7 papers, 2018 to 2025). Aberrant reaction of the microcirculation characterized by movement of fluid and leukocytes from the blood into extravascular tissues. "Moreover, it is also linked to an increase in the number of tissues Th17 cells expressing CCR6, RORγt, and IL-17A in in vivo airway inflammation models." (PMID 41049431, 2025). "The role of CCR6 in renal inflammation is not fully understood, but CCR6 and CCL20 might play a role in the recruitment of T and B cells to organize nodular infiltrates in chronic renal inflammation." (PMID 37092451, 2023). "We next asked whether the 1,25(OH)2D3-treated memory CCR6+ Th cells could contribute to the suppression of synovial inflammation, for which the cells need to be able to migrate toward inflammation." (PMID 31379807, 2019). "In turn, these molecules, especially PGE2, further activate the CCR6+ memTh cells to produce more IL-17A, thereby creating a proinflammatory feedback loop that could drive the chronic synovial inflammation." (PMID 30236152, 2018).
immune diseases (5 papers, 2011 to 2022). "It directly participates in the directional migration of dendritic cells and T cells through the action of ligand CCR6 and plays a role in immune and immune diseases." (PMID 30245729, 2018). "And CCR6+ subset of Tregs, a demonstrated memory/effector phenotype, played an important role in various immune diseases (Kitamura, Farber & Kelsall, 2010)." (PMID 25279261, 2014). "Thus, the macrophage-mediated CCL20/CCR6 axis is involved in the pathogenesis of EMs by promoting the proliferation and migration of ESCs as well as being closely related to immune dysfunction." (PMID 35841069, 2022). "A lack of CCR6 or its ligands, MIP-3α or hBD2, is associated with immune dysfunction including reduced levels of intestinal B cells and regulatory T cells, diminished production of antigen specific IgA, and defects in T cell priming." (PMID 28509877, 2017).
renal disease (4 papers, 2018 to 2025). "Indeed, CCR6 is implicated in lymphocyte recruitment to inflamed tissues, and may be involved in T cell migration to kidneys during renal disease development." (PMID 37885889, 2023). "These receptors, as well as CCR6 and CXCR6, are also involved in T cell recruitment to the kidney during renal disease." (PMID 29868028, 2018).
bacterial infection (3 papers, 2014 to 2022). "Further functional data on the recruitment of neutrophils by CCL20 and CCR6 during acute bacterial infections are sparse." (PMID 24699535, 2014). "Whether splenic follicular T cell CCR6 function would be apparent in more inflammatory settings such as bacterial infection remains an open avenue for investigation." (PMID 35812408, 2022). "We propose that CCR6+, CXCR6+ and αEβ7-expressing intrahepatic MAIT cells are retained close to the bile ducts in steady state to provide protection against ascending bacterial infection from the gut." (PMID 26743076, 2016). "There have been no studies on the role of CCL20 and CCR6 in bacterial infections of the central nervous system." (PMID 24699535, 2014).
liver (3 papers, 2011 to 2022). "Surprisingly, Ccr6-/- mice depleted of macrophages were extremely susceptible to liver injury, which precluded us performing a chronic liver injury model." (PMID 26691857, 2015). "Interestingly, the hepatic number of MPO-positive cells was lower in Ccr6-/- mice compared to wt after chronic liver injury (p<0.05)." (PMID 26691857, 2015).
adenocarcinoma (1 paper, 2011). A common cancer characterized by the presence of malignant glandular cells. "The average CCR6 staining index was 0.75 +/− 0.16 for stage I adenocarcinoma, 1.05 +/− 0.24 for stage II adenocarcinoma and 1.37 +/− 0.22 for stage III adenocarcinoma." (PMID 21949768, 2011). "The increased CCR6 staining index observed in stage III relative to stage I adenocarcinoma was statistically significant P = 0.03." (PMID 21949768, 2011). "In this array, we found a higher CCR6 staining index among advanced stage adenocarcinomas." (PMID 21949768, 2011).
cardiovascular disease (1 paper, 2021). "As α-gal IgE sensitization has been shown to associate with CAD, we further explored roles of CCR6 and CXCR4 in cardiovascular disease." (PMID 35097011, 2021).
ischaemic heart disease (1 paper, 2017). "Taken together, these studies support the hypothesis that CCL20-neutralising antibodies administered to patients with ischaemic heart disease have the potential to suppress the migration of CCR6+ IL-17A-producing γδT cells and improve prognosis." (PMID 28798316, 2017).
neurological disorders (1 paper, 2020). "Another gene worth noting is Kng2, that appears as a hub in the Ccr6 PPI subnetwork, implicating that the Kallikrein-kinin system (KKS) mediate the pathophysiological features of neurological disorders, including GWI." (PMID 32922257, 2020).
vasculopathy (1 paper, 2021). "This is the first report demonstrating a potential contribution of CCR6 to the development of SSc vasculopathy as an inflammation-associated angiogenic factor." (PMID 34774095, 2021). "Given that FLI1 bound the CCR6 promoter in HDMECs, CCR6 is a member of molecules involved in the mechanism by which FLI1 deficiency promotes the development of SSc vasculopathy." (PMID 34774095, 2021). "Based on these backgrounds, we investigated the potential role of CCL20/CCR6 in SSc vasculopathy and the contribution of FLI1 deficiency to this process by a series of experiments with clinical samples, cultured endothelial cells, and animal models." (PMID 34774095, 2021). "With respect to CCL20, we have recently found that serum CCL20 levels correlate with mean pulmonary arterial pressure (mPAP) in SSc patients, suggesting that the CCL20/CCR6 axis underlies the developmental mechanism of SSc vasculopathy." (PMID 34774095, 2021). "The increased expression of endothelial CCR6 due to FLI1 deficiency may contribute to the development of SSc vasculopathy." (PMID 34774095, 2021). "Taken together with our recent data regarding the association of the CCL20/CCR6 axis with SSc-PAH, we hypothesized that FLI1 deficiency regulates the CCL20/CCR6 axis in the context of SSc vasculopathy." (PMID 34774095, 2021). "Considering this point, the blockade of CCR6 is likely a potential therapeutic strategy against SSc vasculopathy." (PMID 34774095, 2021). "To further confirm if CCR6 upregulation is involved in the development of SSc vasculopathy, we evaluated the effect of Ccr6 siRNA on the vascular aspect of BLM-treated mice, a widely recognized animal model of SSc." (PMID 34774095, 2021). "This study was undertaken to investigate the role of the CCL20/CCR6 axis in the development of SSc vasculopathy because serum CCL20 levels correlate with mPAP values in SSc patients." (PMID 34774095, 2021). "Considering a proangiogenic effect of CCL20 on endothelial cells via CCR6, the CCL20/CCR6 axis may contribute to the development of SSc vasculopathy." (PMID 34774095, 2021). "Taken together with evidence that the CCL20/CCR6 axis functions as a potent pro-angiogenic regulator, CCR6 upregulation may be involved in the development of SSc vasculopathy." (PMID 34774095, 2021). "Taken together, these results suggest that CCL20 secreted from dermal fibroblasts plays a role in the early stage of dcSSc (disease duration of < 2 years), while CCR6 up-regulation in endothelial cells contributes to the development of SSc vasculopathy throughout the whole disease course." (PMID 34774095, 2021).
CCR6 also shares sentences with these, for which no sentence is quoted: kidney cancer (4 papers); alopecia (3); esophageal squamous cell carcinoma (3); hypersensitivity pneumonitis (3); autoimmune encephalitis (2); intestinal inflammation (2); juvenile dermatomyositis (2); juvenile idiopathic arthritis (2); leukemia (2); osteoarthritis (2); pulmonary sarcoidosis (2); Sepsis (2); synovitis (2); abdominal aortic aneurysm (1); acne (1); acute myeloid leukemia (1); alcoholic hepatitis (1); allergic rhinitis (1); ANCA-associated vasculitis (1); anorexia nervosa (1); Anxiety (1); autoimmune liver disease (1); Behcet disease (1); bone cancer (1); brain ischemia (1); central obesity (1); Chagas cardiomyopathy (1); chronic thromboembolic pulmonary hypertension (1); colon adenocarcinoma (1); coronary artery disease (1).
A further 48 diseases each share a sentence with CCR6 in 1 paper.